RASSF1 (Ras association domain family member 1)
Diseases named in the same sentence as RASSF1 in open-access papers (continued):
Sharing a sentence is not in itself a finding about the gene and the disease.
tumor (593 papers, 2002 to 2026). "These DNMTs were found to bind to promoter region of the tumor suppressing gene, Ras association domain family member 1 (RASSF1), inhibiting its expression." (PMID 40264508, 2025). "For instance, in a wide variety of sporadic malignancies, promoter methylation of the RASSF1 gene is associated with tumour invasion and metastasis." (PMID 36759723, 2023). "The reduced expression of RASSF3, a paralog of RASSF1 that has already been implicated as a tumour suppressor in UM, following treatment with trametinib is partially recovered by the addition of cerivastatin." (PMID 36765842, 2023). "Analysis of associations between biomarkers and tumor grading revealed statistically significant differences in promoter hypermethylation of RASSF1, ADAMTS12 (G1 vs. G2), and MT1E (G2 vs. G3) (p < 0.05)." (PMID 36499753, 2022). "This signaling pathway also plays a role in cell-cycle mediation and in the induction of apoptosis, and is thought to be tumor-suppressing given the silencing of Rassf1 and somatic mutation of MAP3K in many cancers." (PMID 33776953, 2021). "Among them, the Ras-association domain family-1 (RASSF1) gene is a major tumor suppressor gene that inhibits the RAS pathway, which is upregulated in the majority of PCs40,41." (PMID 34321527, 2021). "Specific methylation of the RASSF1‐1α promoter and loss of the RASSF1A isoform is a frequent event in many tumor types and offers closer association with cancer progression and poor overall survival." (PMID 34532864, 2021). "Further study demonstrated that such improvement was attributed to re-expression of Ras association domain family member 1A (RASSF1A), a well-known tumor suppressor gene." (PMID 32457835, 2020). "For instance, methylation of HIC ZBTB Transcriptional Repressor 1 (HIC1) and Ras Association Domain Family Member 1 (RassF1A) tumor suppressor genes was sufficient to transform bone marrow MSCs into malignant cells endowed with tumor‐initiating capabilities." (PMID 32922961, 2020). "The Ras association domain family member 1A (RASSF1A) is one of the most frequently reported tumor suppressor genes that is inactivated by promoter hypermethylation in PDAC." (PMID 32457835, 2020). "Recently, it has been shown that the Ras association domain family member 1 (RASSF1) can be a tumor suppressor controlling cell proliferation and apoptosis." (PMID 31139559, 2019). "For this purpose, four tumour-suppressor genes: Ras Association Domain Family Member 1 (RASSF1), Paired Box 1 (PAX1), Cadherin 1 (CDH1) and Phosphatase and Tensin Homolog (PTEN) were analysed." (PMID 31450846, 2019). "Ras association domain-containing protein 1 is a protein that, in humans, is encoded by the RASSF1 gene, a putative tumor suppressor, involved in cell cycle control and breast carcinogenesis." (PMID 31533668, 2019). "RARB and RASSF1 are important tumor suppressors and loss of expression is associated with a growth advantage and immortalization of tumor cells." (PMID 29851970, 2018). "RASSF1, a member of the Ras association domain family, is known as a tumour suppressor that inhibits RAF1 signalling and activates MST131." (PMID 28205554, 2017). "The RASSF1 gene frequently shows allelic loss in many types of solid tumor, and the RASSF1A, its major isoform, is a tumor suppressor frequently inactivated in cancer cells as a result of hypermethylation of a promoter CpG island." (PMID 27765918, 2016). "Because the ras association domain family 1(RASSF1) regulates both the cell cycle and apoptosis, it is thought to function as a tumor suppressor." (PMID 27230238, 2016). "At the present time, there are ten known members of the Ras-association domain family (RASSF), RASSF1-10, several of which are believed to be tumor suppressor genes." (PMID 26334503, 2015). "In a wide variety of sporadic malignancies, promoter methylation of the RASSF1 gene is associated with tumor invasion and metastasis." (PMID 26549256, 2015).
tumor (continued). "The RASSF1 (Ras association domain family 1) family represents a class of Ras effector proteins that have tumor suppressor properties." (PMID 24790823, 2014). "Proteins from the Ras association family (Rassf, especially Rassf1 and Rassf5) are tumor suppressors that are activated by Ras-GTP, triggering apoptosis via e.g., activation of mammalian sterile 20-like (MST1) kinase." (PMID 24216995, 2013). "The RASSF1 (Ras-association domain family 1) family of proteins represents a class of Ras effectors that possess tumor suppressive properties." (PMID 23139773, 2012). "Ras Association Domain Family 1 (RASSF1) is a putative tumor suppressor gene localized at chromosome 3p21.3 that has been reported to inhibit tumor growth in in vitro and in vivo systems." (PMID 21838870, 2011). "No direct association between promoter hypermethylation in MGMT or RASSF1 and age, sex, smoking, alcohol drinking, or tumor stage was observed, in agreement with recently reported data." (PMID 19807915, 2009). "Clinical evidence also suggests that patients with hypermethylation on the promoter region of tumor suppressive genes, such as Ras association domain family member 1 (RASSF1A) 35, BRMS133, and breast cancer type 1 susceptibility gene (BRCA1) 36, 37, 38, are associated with poor prognosis." (PMID 29473320, 2018). "Treatment with piR-8041 led to increased expression of tumor suppressor RASSF1, which encodes a tumor suppressor shown to mediate cell cycle arrest at the G1/S-phase transition via inhibition of cyclin D1 accumulation and also shown to induce apoptotic cell death." (PMID 30701019, 2018). "Furthermore, we found associations between RASSF1 promoter methylation and aggressive tumor characteristics, such as HER2 expression and high tumor grade (G3)." (PMID 29731982, 2018). "It is thought that RASSF1 may belong to the class of haplo-insufficient tumor suppressor genes that promotes tumor formation through the inactivation of only one allele (Schagdarsurengin, Gimm, Hoang-Vu, Dralle, & Pfeifer, 2002)." (PMID 27158284, 2015). "Additionally, BMP signaling plays a role in the Hippo signaling pathway by inducing the phosphorylation of YAP (inactivated form) and stimulating the Ras association domain family (RASSF1; an upstream regulator of the Hippo signaling pathway) to inhibit tumor development and progression." (PMID 32731498, 2020). "In contrast, HNF4A, RASSF1, SPARCL1, and LHPP are associated with favourable outcomes: HNF4A regulates hepatocyte differentiation, RASSF1 acts as a tumour suppressor, SPARCL1 inhibits angiogenesis and metastasis, and LHPP suppresses tumour growth." (PMID 41007296, 2025). "This leads to the hypermethylation of tumor suppressor gene promoters, such as hypermethylated in cancer transcriptional repressor 1 (HIC1), RAS association domain family member 1 (RASSF1A), and caspase 8 (CASP8), which results in tumor proliferation." (PMID 39056791, 2024). "RASSF1 is an extensively researched gene known for its tumor suppressor function, engaging in the control of cell growth, modulation of the cell cycle, and initiation of programmed cell death." (PMID 38891848, 2024). "This assay is based on epigenetic changes associated with the risk of PC development existing/occurring adjacent to tumor foci (halo effect) and evaluates quantitatively the DNA methylation level of GSTP1, APC, and RASSF1." (PMID 38254807, 2024). "Several of the genes that demonstrated a putative role as predictive biomarkers are either well-known tumor suppressors (RASSF1, XAF1, ASC/TMS1, ASPP1, DAB2IP) or DNA damage response regulators (SLFN11)." (PMID 39051186, 2024). "RASSF-1, located on chromosome 3p21.3, is frequently hypermethylated in TGCT, leading to its silencing and loss of tumor-suppressive function." (PMID 37569569, 2023).
tumor (continued). "RASSF1A, a member of the RASSF1-6 family, is a known tumor suppressor and has been reported to be hyper-methylated, and thus inactivated, in a number of cancers." (PMID 37835395, 2023). "RASSF1, along with its role in cell-cycle control, cellular adhesion, motility and apoptosis, has been identified as a tumor suppressor gene." (PMID 37508506, 2023). "RASSF1 is an established tumor suppressor that induces cell cycle regulation and apoptosis and is inactivated in various cancers by hypermethylation or mutations." (PMID 36723232, 2023). "Genetic damage to tumor suppressors located in these chromosomal regions (such as CDKN2A, Ras association domain family member 1 (RASSF1A), and TGFBR2) is a key component of genomic instability in NPC." (PMID 36135044, 2022). "Some identified genes, such GSTP1, RARB, and RASSF1, which were previously suggested as methylation biomarkers for PCa, showed DMRs in tumor tissues." (PMID 35053153, 2021). "Individual RASSF1 CpG site analysis allows separation of epigenetic silencing at RASSF1‐1α from RASSF1‐2γ and therefore study of the differential contribution of the tumor suppressor RASSF1A from the oncogenic RASSF1C isoform to disease progression." (PMID 34532864, 2021). "The TCGA database incorporates tumor methylation signal from 52 CpG sites across the RASSF1 gene, determined using an Illumina HM450K BeadChip." (PMID 34532864, 2021). "Pathway analysis showed activation of the transforming growth factor-β pathway in YSTs, which is associated with the overexpression of GATA6 and FOXA2 and the hypermethylation of tumor-suppressor genes (e.g., RASSF1, RUNX3, HIC1, or APC)." (PMID 32999426, 2020). "The protein levels of Rassf1, Mst1, Mst2, Sav1, Mob1, and p-Mob1 increased in the UA-treated xenograft tumor tissues as compared with those in the control tumor tissues." (PMID 31547587, 2019). "Curcumin decreased tumor size, which correlated with specific CpG site hypomethylation of the RASSF1 promoter." (PMID 31323834, 2019). "Our data suggest that deregulation of P4HA2 levels in RASSF1‐methylated tumours is a key factor behind the poor prognostic value of these cancers." (PMID 31268606, 2019). "UHRF1 is also associated with epigenetic silencing of various tumor suppressors and other tumor-related genes, including CDKN2A, RB, BRCA1, RASSF1, PPARG, APC, CDH1, and RGS2." (PMID 31064417, 2019). "RASSF1 has been one of the most studied tumor suppressor genes in this context because its locus was cloned from a region in chromosome 3p21 that is frequently lost in lung cancer." (PMID 30657883, 2019). "Smurf1 interacts with a tumor suppressor, RASSF1A (Ras association domain family member 1), to enhance the ubiquitination of RhoA; therefore, RhoA levels are decreased and tumorigenesis is suppressed." (PMID 31248165, 2019). "Significantly higher RASSF1 methylation levels were observed in association with BRCA1/2 mutations, HER2 expression and high tumor grade." (PMID 29731982, 2018). "Significantly higher RASSF1 methylation levels were observed in cases positive for BRCA1/2 mutation (p=0.008), HER2 expression (p=0.01), and with high tumor grade (G3) (p=0.008)." (PMID 29731982, 2018). "CART and ctree analysis identified the combination of L1RE1 and RARB as well as L1RE1 and RASSF1 as independent methylation markers with high discriminative power between tumor and benign tissue (for each combination, 91% specificity and 100% sensitivity)." (PMID 29851970, 2018). "In our study, AR, RASSF1 and hTERT were the genes that most frequently showed higher methylation levels in tumor compared to normal breast tissues, with AR showing a statistically significant difference." (PMID 29731982, 2018). "RASSF1 is a putative tumor suppressor gene that controls tumor growth by inhibiting the RAS pathway." (PMID 26754001, 2016).
tumor (continued). "Overexpression of UHRF1 occurs in many types of cancer, and aberrantly expressed UHRF1 causes cancer cell activation through hyper-methylation of tumor-suppressor genes such as BRCA1, CDKN2A, p73, and RASSF1." (PMID 27072587, 2016). "It is true that of all the genes in the 3p21.3 critical region RASSF1 has been the most comprehensively studied at the genetic, epigenetic and functional level, and its role as a tumor suppressor gene has been proven." (PMID 26112163, 2015). "Comparisons between FTC-Classic and FTC-Hurthle tumor tissue demonstrated significant differences in RASSF1 methylation levels (p<0.001) with higher levels in the FTC-Classic tumor tissue." (PMID 27158284, 2015). "RASSF1 is involved in apoptosis, cell cycle control, regulation of microtubule stability, and tumor suppression and is epigenetically silenced in human cancers." (PMID 26269600, 2015). "Genetic alterations in genes along pathways involving RASSF1’s tumor suppressor role are also a consideration." (PMID 27158284, 2015). "RASSF1 gene hypermethylation was also differently distributed with respect to the luminal tumor subtypes, although the pattern was less significant (p = 0.046)." (PMID 26284587, 2015). "RASSF1 was methylated in 74.1% of the patients, which indicates its value as a overall tumor marker for this disease, as described in breast and other types of cancer." (PMID 26284587, 2015). "The RASSF1 gene showed evidence of de novo methylation around a CpG island promoter in one of the three tumors examined, tumor 32T while a second alternative promoter was located in non-island sequence and a third was within a CpG island." (PMID 25960928, 2014). "DIPP-3α is identified as interacting with Ras association domain-containing protein 1 (UniProtKB ID Q9NS23; gene name RASSF1), which is a potential tumour suppressor that regulates aspects of cell cycle progression and apoptosis." (PMID 24152294, 2014). "RASSF1 has been shown to be transcriptionally silenced by promoter methylation and are frequently methylated in various tumor types." (PMID 23533570, 2013). "Statistical analysis revealed 3 genes (HIC1, GSTP1, and RASSF1) capable of significantly predicting tumor recurrence." (PMID 24252461, 2013). "Frequent inactivation of several 3p21.3 genes as functional TSGs, such as RASSF1 and BLU, by promoter CpG methylation had been identified associated with tumor initiation and progression." (PMID 23050586, 2012). "In this study we conducted an exhaustive analysis of RASSF1 methylation status in order to define its putative role as a possible tumor specific and transcription regulatory event occurring in PET." (PMID 21838870, 2011). "MST1 serine-threonine kinase, a component of the RASSF1-LATS tumor suppressor network, binds androgen receptor (AR), but the kinase activity of MST1 is not involved in inhibition of AR." (PMID 22035226, 2011). "Among the genes differentially methylated are number of well- known tumor suppressor genes, namely RASSF1, DLG1, DLC1 and PRDM2, as well as various other tumor related genes." (PMID 24212793, 2011). "Previous studies showed that NORE1A mediates Ras-dependent apoptosis and suppresses tumor cell growth and colony formation, and the proapoptotic effect of RASSF1 requires the heterodimerization with NORE1A." (PMID 20969767, 2010). "Significant tumour-specific promoter methylation (for Ca ex PSA) is apparent at RASSF1 by comparison with PSA." (PMID 21063414, 2010). "Among 8 RASSF genes identified, RASSF1 was the most well-characterized tumor suppressor, which exhibits a frequent epigenetic inactivation in various types of human neoplasms, including lung and breast cancers." (PMID 20969767, 2010). "In common with other cancers, WTs also show tumour suppressor gene silencing which includes genes such as HACE1 (73% of tumours analysed), RASSF1 (56%), CASP8 (43%), MGMT (30%), RASSF5/NORE1 (15%), and CDKN2A (10–15%)." (PMID 19956686, 2009).
tumor (continued). "Expression of the longest splice isoform of the RASSF1 gene, RASSF1A, is downregulated by selective hypermethylation of its promoter CpG islands in at least 37 tumour types, according to the recent review." (PMID 19098985, 2008). "RASSF1 proteins are potential Ras effectors and the major isoform, RASSF1A, is an important human tumour suppressor protein acting at G1/S phase of cell-cycle progression." (PMID 16969349, 2006). "A new family of tumor suppressor genes encoding RAS-binding proteins and named RASSF1 has been recently discovered." (PMID 16606445, 2006). "Recently, the ras effectors/tumour suppressors RASSF1 and NORE1 were found to be inactivated by promoter hypermethylation in a variety of human tumours." (PMID 16265349, 2005). "Analyzing two other tumor-suppressors–PITX2 and RASSF1, treatment with S. officinalis did not cause changes in methylation of their promoter regions when compared to untreated (control) tumor samples." (PMID 38464730, 2024). "Therefore, we reviewed RNA-seq data and found that the tumor suppressor gene Rassf1 was significantly up-regulated, and that Rassf1 enhanced Mst1/2 activity by phosphorylation." (PMID 38493147, 2024). "1A is a tumor suppressor gene epigenetically silenced in cancer, without epigenetic loss of the other isoforms of RASSF1." (PMID 36983040, 2023). "The RASSF1 gene showed hypermethylation in tumor tissue in both BRAF mutant and wild-type cases." (PMID 36975440, 2023). "Similarly, the RASSF1 gene presents RASSF1A as a tumor suppressor and RASSF1C with potential oncogenic roles." (PMID 38003596, 2023). "CASP8, RASSF1 were the most frequently methylated genes in all tumor samples." (PMID 34771655, 2021). "Finally, our experiment focusing on epigenetic modulation of clove buds showed a demethylation of the promoter of RASSF1 tumor suppressor in vivo." (PMID 32204409, 2020). "RASSF1 gene is a potential tumor suppressor required for death receptor-dependent apoptosis." (PMID 32647312, 2020). "In YSTs, several tumor-suppressor genes (such as RASSF1 or APC) are hypermethylated." (PMID 32999426, 2020). "RASSF1 was among the top 10 downregulated mRNAs in tumour tissues." (PMID 30507050, 2019). "Tumor latency was decreased in SB mice on the Rassf1-null background." (PMID 31338332, 2019). "The 3p.21.31 region may harbor candidate tumor suppressor genes due to the frequent copy number loss in various cancer types, including HYAL2, TUSC2, RASSF1, ZMYND10, NPRL2, CYB561D2, TMEM115. and CACNA2D2." (PMID 31323949, 2019). "L1RE1 and RASSF1 separated control samples from tumor samples in the same way." (PMID 29851970, 2018). "In addition, RASSF1 has been shown to be epigenetically silenced in various tumours and upon E2 exposure." (PMID 29748642, 2018). "Based on our results L1RE1 and RARB as well as L1RE1 and RASSF1 might serve as biomarkers for less invasive investigations such as liquid-biopsies or tumor biopsies (e.g., derived by endobronchial ultrasound transbronchial needle aspiration (EBUS-TBNA))." (PMID 29851970, 2018). "In particular, RASSF1 showed a pronounced increase of methylation frequency with tumor grade." (PMID 29851970, 2018). "RASSF1 is suggested to have tumor suppressor functions through inhibition of the Ras pathway." (PMID 30197755, 2018). "However, combinations of two methylation biomarkers, i.e. L1RE1 and RARB or L1RE1 and RASSF1, were sufficient to discriminate tumor from benign tissue with 91% specificity and 100% sensitivity using CART classification." (PMID 29851970, 2018).